FOXM1 (forkhead box M1)
Diseases named in the same sentence as FOXM1 in open-access papers (continued):
Sharing a sentence is not in itself a finding about the gene and the disease.
latent infection (1 paper, 2023). "The cell proliferation marker MKI67 as well as genes involved in G1-S and G2-M transition, such as CDK1, CDK2, CCNE2, PRIM2, AKT1, and FOXM1, were significantly downregulated in latent infection compared to actively infected cells." (PMID 38038477, 2023).
Lewis lung carcinoma (1 paper, 2024). "Interestingly, a recent study showed that inhibition of FOXM1 using Thiostrepton in Lewis lung carcinoma cells caused an increase in the number of intratumoral CD3+ T cells, in line with our observations." (PMID 38373993, 2024).
lipid metabolic disorders (1 paper, 2025). "Furthermore, treatment with the antioxidant resveratrol (RSV) and its nanoformulation (RSV-NPs) markedly inhibited tumor growth in mice with lipid metabolic disorders, highlighting their potential to counteract progesterone resistance by disrupting this OLR1/FOXM1/FGF19 axis." (PMID 41270216, 2025).
liver cirrhosis (1 paper, 2018). "FoxM1- and HMGCR-high group had a statistically significant lower rate of liver cirrhosis of liver histology than FoxM1- and/or HMGCR-low group (p = 0.0337) and FoxM1- and SREBP2-high group had a statistically significant higher PIVKA-II level than FoxM1- and/or SREBP2-low group (p = 0.0294)." (PMID 29765517, 2018).
mucinous lung adenocarcinoma (1 paper, 2017). "To demonstrate that the FOXM1 regulation of the mucinous phenotype is not limited to one cell line, we also inhibited FOXM1 in H2122 cells, another human mucinous lung adenocarcinoma with an activating mutation in Kras (KrasG12C)." (PMID 29267283, 2017). "In an orthotopic xenograft model of human mucinous lung adenocarcinoma, inhibition of FOXM1 suppressed mucinous characteristics and reduced the tumor invasion and metastasis." (PMID 29267283, 2017). "Mice co-expressing both the KrasG12D and the FoxM1-ΔN transgenes (SPC-rtTA/ TetO- KrasG12D/ TetO-FoxM1-ΔN,) developed mucinous lung adenocarcinomas compared to mice expressing KrasG12D alone." (PMID 29267283, 2017). "Thus, FOXM1 is essential for AGR2 expression and the mucinous phenotype in human mucinous lung adenocarcinoma cell lines." (PMID 29267283, 2017). "Thus, FOXM1 induces AGR2 in mouse and human mucinous lung adenocarcinomas." (PMID 29267283, 2017).
myasthenia gravis (1 paper, 2023). Myasthenia gravis (MG) is a rare, clinically heterogeneous, autoimmune disorder of the neuromuscular junction characterized by fatigable weakness of voluntary muscles. "FOXM1 was found to be involved in the regulation of myasthenia gravis, which is a transcription factor regulating myasthenia-gravis-related miRNAs." (PMID 37238726, 2023).
myelodysplastic syndrome (1 paper, 2023). A clonal hematopoietic disorder characterized by dysplasia and ineffective hematopoiesis in one or more of the hematopoietic cell lines. "In patients with del(5q) myelodysplastic syndrome (MDS), the transcription factor FOXM1 is frequently downregulated in CD34+ cells." (PMID 37526082, 2023).
Myocardial fibrosis (1 paper, 2023). "And the activated YAP further phosphorylates protein kinase B (AKT) and reduces glycogen synthase kinase‐3 β (GSK3β) activity, ultimately causing overexpression of forkhead box M1 (FOXM1) in cardiomyocytes and leading to myocardial fibrosis." (PMID 37576865, 2023).
Neonatal sepsis (1 paper, 2025). Systemic inflammatory response to infection in newborn babies. "We identified key TFs implicated in driving neonatal sepsis mortality with Forkhead box M1 (FOXM1) – a master regulator of cell cycle regulation and T-lymphocyte survival – emerging as the only TF identified through both computational approaches used." (PMID 40655143, 2025). "Future mechanistic studies are warranted to elucidate the role of FOXM1 and other TFs in immune dysregulation and explore their potential as therapeutic targets in neonatal sepsis." (PMID 40655143, 2025).
nephrotic syndrome (1 paper, 2025). A collection of symptoms that include severe edema, proteinuria, and hypoalbuminemia; it is indicative of renal dysfunction. "As such, the upregulation of Mki67 and Foxm1 may indicate the recovery process of tubular cells from micro-injury induced by nephrotic syndrome." (PMID 39666151, 2025). "mRNA expression of Foxm1 and Mki67 also significantly increased in this nephrotic syndrome model." (PMID 39666151, 2025). "First, although we demonstrated the changes in mRNA and protein expression in nephrotic syndrome, the specific factors responsible for upregulating cell proliferation-related genes, including Foxm1, were not clarified in this study." (PMID 39666151, 2025).
neuroendocrine neoplasm (1 paper, 2015). Endocrine tumors, also referred to as neuroendocrine tumors (NETs), are defined by a common phenotype which is characterized by the expression of general markers (neuron specific enolase, chromogranin, synaptophysin) and hormone secretion products. "The role of FOXM1 in neuroendocrine neoplasms has rarely been explored to date, but it has been recently described as marker for subtyping neuroendocrine lung cancer." (PMID 25797272, 2015).
pancreatic NENs (1 paper, 2015). "Given the fact that everolimus is a well-established therapy in pancreatic NENs, but its efficacy is limited, we propose a potential for the assessment of a combination therapy with FOXM1 inhibitors." (PMID 25797272, 2015).
preeclampsia (1 paper, 2021). Preeclampsia is a hypertensive disorder of pregnancy that is characterized by new-onset hypertension with proteinuria presenting after 20 weeks of gestation, and depending on mild or severe forms may initially present with severe headache, visual disturbances, and hyperreflexia. "It was reported that FOXM1 expression was downregulated in the placental tissues of patients with preeclampsia, and FOXM1 silencing significantly decreased cell proliferation and migration." (PMID 33502747, 2021).
Promyelocytic leukemia (1 paper, 2019). "Promyelocytic leukemia may also interfere with other components of the FOXM1 network to indirectly regulate its expression." (PMID 30927552, 2019).
pterygium (1 paper, 2020). A wedge-shaped fibrovascular lesion arising from the bulbar conjunctiva and extending to the cornea. "In addition, the mRNAs in both networks are enriched in PID FOXM1 PATHWAY, indicating that LINC00472 is likely to regulate the growth of pterygium through PID FOXM1 PATHWAY." (PMID 33299863, 2020). "We presume that the LINC00472 network might function in pterygium via the FOXM1 PATHWAY, especially through the regulation of CCNB1, MYC, ERBB4, RELN, RB1, and CDH2 in the ceRNA network." (PMID 33299863, 2020). "This indicated that LINC00472 might play an important role in pterygium through FOXM1 PATHWAY." (PMID 33299863, 2020).
respiratory failure (1 paper, 2023). The significant impairment of gas exchange within the lungs resulting in hypoxia, hypercarbia, or both, to the extent that organ tissue perfusion is severely compromised. "Conditional deletion of FoxM1 in respiratory epithelium inhibits expression of surfactant proteins and lung maturation, contributing to neonatal respiratory failure." (PMID 36788588, 2023).
salivary gland epidermoid carcinoma (1 paper, 2016). "Our data indicated that the p63-FOXM1 axis is also present in submaxillary salivary gland epidermoid carcinoma (A253) cells, suggesting that ΔNp63 amplification could, at least in part, be responsible for FOXM1 over-expression in epithelial cancers." (PMID 27385468, 2016).
signet ring cell carcinoma (1 paper, 2016). A usually aggressive, poorly differentiated invasive adenocarcinoma characterized by the presence of malignant glandular cells in which the nucleus is pressed to one side by the presence of intracytoplasmic mucus. "Signet ring cell carcinoma, the subtype with the lower overall expression of GPC3 than adenocarcinoma, shows significantly higher levels of FoxM1 compared to adenocarcinoma (p=0.015)." (PMID 27259271, 2016).
skin aging (1 paper, 2021). The gradual irreversible changes in structure of skin that occur as a result of the passage of time.. "As TF FOXM1, which was modified by phosphorylation, was activated, the target gene CAT was upregulated to inhibit ROS accumulation in both young-adult and middle-aged skin aging." (PMID 34073305, 2021).
skin basal cell carcinoma (1 paper, 2020). The most frequently seen skin cancer. "Microarray analysis based study has identified that Forkhead box M1 (FOXM1) positively regulates the expression of KIF20A and upregulation of FOXM1 is associated with several normal and transformed cells of hepatocellular and skin basal cell carcinoma." (PMID 32752229, 2020).
speech language disorder (1 paper, 2015). "For example, the R553H mutation in FOXP2 (equivalent to FOXM1 R286) is associated with development of a severe speech language disorder, while a mutation of the same arginine residue in FOXC2 (R121C) is associated with a developmental disorder affecting the lymphatic vasculature system." (PMID 26100407, 2015).
Stroke (1 paper, 2025). Sudden impairment of blood flow to a part of the brain due to occlusion or rupture of an artery to the brain. "This work primarily advances the understanding of the molecular mechanisms governing exosome-mediated neuroprotection and explicitly frames in vivo validation of the hAECs-Exos/FoxM1 axis as a key next step to move toward potential clinical application in stroke treatment." (PMID 41154771, 2025). "Notably, our study not only validates FoxM1 as a key downstream effector of hAECs-Exos but also positions it as a superior target compared to canonical stroke-related transcription factors, offering a more comprehensive strategy for interrupting the ischemic cascade and improving stroke outcomes." (PMID 41154771, 2025).
testicular tumors (1 paper, 2020). "In tumor samples, liver, cervical and testicular tumors had higher levels of FOXM1." (PMID 33253193, 2020).
thymoma (1 paper, 2022). A neoplasm arising from the epithelial cells of the thymus.
uterine cancer (1 paper, 2025). Primary or metastatic malignant neoplasm involving the uterine corpus and/or the cervix. "FOXM1 is consistently upregulated, being in the top 150 of the most upregulated transcripts in some cancers (bladder, breast, lung squamous, and uterine cancers)." (PMID 39858603, 2025).
Uterine leiomyoma (1 paper, 2021). The presence of a leiomyoma of the uterus. "This study provides insight into a mechanism whereby Cd, a metalloestrogen, induced cell proliferation in hormonally responsive human uterine leiomyoma (ht-UtLM) cells, and the molecular basis of a FOXM1 and Cyclin D1-regulated event downstream of MAPK induced by Cd." (PMID 33818655, 2021). "Cd concurrently increases the expression of FOXM1 and Cyclin D1 downstream of MAPK44/42, which in turn upregulates the kinase Aurora B, leading to Histone H3 phosphorylation at serine 10 site, and resulting in human uterine leiomyoma cell mitosis." (PMID 33818655, 2021).
vascular cancer (1 paper, 2017). A malignant neoplasm arising from the blood vessels. "Knockdown FoxM1 decreases the invasion of SiHa cells and reconstitution of Sufu rescues the invasion of these cells.Finally, overexpression of Sufu is significantly associated with differentiation grade, FIGO stage, Depth of stromal invasion and vascular cancer embolus." (PMID 29371981, 2017).
Wilms tumor (1 paper, 2013). An embryonal neoplasm characterized by the presence of epithelial, mesenchymal, and blastema components. "Increasing evidence has shown that miR-370 regulates a number of target genes, including Wilms tumor gene on the X chromosome, insulin receptor substrate 1, Forkhead box protein O1 and FoxM1 in AML by our group." (PMID 24148180, 2013).
cancer (948 papers, 2007 to 2026). A tumor composed of atypical neoplastic, often pleomorphic cells that invade other tissues. "Although depletion of the Forkhead box protein M1 (FoxM1) transcription factor is reported to be the main cause of the cytotoxicity of thiostrepton in cancer, other causes have been discussed." (PMID 40687439, 2025). "The genomic location of the FOXM1 gene is on chromosomal band 12p13.33 in humans and amplification of this segment is a common scenario in FOXM1-associated cancers." (PMID 40630538, 2025). "We identified E2F4 and FOXM1 as transcription factors strongly associated with adaptation to aneuploidy in vitro and in cancers and validated this finding." (PMID 39930267, 2025). "This dual role in promoting the cell cycle and preserving genomic stability makes FOXM1 the final molecular judge of tumor initiation, as it controls both a source of mutations and the proliferative hallmark of cancer." (PMID 39858603, 2025). "One such driver has been shown to be the FOXM1 gene, which has previously been linked to cancer initiation and progression." (PMID 39858603, 2025). "FOXM1 has been implicated in various hallmarks of cancer, including cell cycle progression and regulation of the tumour microenvironment as well as in LUSC progression and in the regulation of SOX2 transcription." (PMID 41388088, 2025). "Heightened FOXM1 expression shows promise as a potential diagnostic and prognostic indicator for cancer." (PMID 39781349, 2025). "Especially through WGCNA analysis, we found that gene enrichment in the green-yellow module is associated with the FOXM1 pathway and retinoblastoma (RB) pathway, which play a central role in cancer cell cycle regulation, proliferation, and DNA repair." (PMID 40313958, 2025). "While FoxM1 has been widely studied as an oncogenic driver in tumor biology and is considered a diagnostic and prognostic biomarker for various cancers, its functions extend beyond oncology." (PMID 41154771, 2025). "Acquired resistance to FOXM1 inhibition is associated with increased expression of cancer stem-cell markers and proteins that repress ferroptosis, enabling cell survival and drug resistance." (PMID 38980505, 2024). "Recent studies have also linked FOXM1 dysregulation to the development of cancer treatment resistance and the course of the disease." (PMID 38922530, 2024). "FOXM1 is a proliferation-associated transcription factor that plays a critical role in cancer development and progression." (PMID 39596041, 2024). "FOXM1 is an oncogenic transcription factor that promotes proliferative signaling by regulating the cell cycle, and a high level of FOXM1 in many types of cancers is associated with a more aggressive phenotype and less good patient survival." (PMID 38980505, 2024). "The increased level of FOXM1 in different types of cancer induces cancer progression, invasion, metastasis, and tumor-associated angiogenesis." (PMID 38398147, 2024). "Over the years, O-GlcNAcylation has been linked to multiple cancer hallmarks through the modification and modulation of many cancer-relevant proteins such as FOXM1, c-MYC, β-catenin, snail and NF-kB." (PMID 39413067, 2024). "FOXM1 is an oncogenic transcription factor that has been implicated in cancer progression, metastases, and chemotherapy resistance." (PMID 38398147, 2024). "FOXM1 is overexpressed in various human cancers and is implicated in several cancer processes, such as proliferation, metastasis, and therapeutic resistance." (PMID 38425293, 2024). "While multiple mechanisms can mediate drug resistance development, FOXM1 is repeatedly identified as a common factor associated with weaker responses to conventional cancer therapies by regulating several target genes associated with cell cycle and DNA repair." (PMID 38697979, 2024). "Overexpression and gene amplification of FOXM1 are linked to several types of cancer and this association has been found to result in a poor prognosis 51,52,56–59." (PMID 38374400, 2024).
cancer (continued). "A previous study verified that FOXM1 expression is elevated in various human cancers and is associated with tumor development." (PMID 38342795, 2024). "FOXM1 is highly expressed in many different cancers, and its expression is associated with a higher tumor stage and worse patient-related outcomes." (PMID 38398147, 2024). "Dysregulation of FOXM1 has been linked to numerous human diseases, including various cancers, making it an attractive target for therapeutic applications." (PMID 38918225, 2024). "Specifically, FOXM1's upregulation and amplification are implicated in various cancers, including NSCLC, contributing to processes such as invasion, movement, new blood vessel formation, cellular differentiation, and resistance to treatments." (PMID 38577601, 2024). "It is known that the loss of FOXM1 in cancer cells leads to mitotic spindle dysregulation and mitotic catastrophe." (PMID 38398147, 2024). "Forkhead box protein M1 (FOXM1) is often overexpressed in human cancers and strongly associated with therapy resistance and less good patient survival." (PMID 38697979, 2024). "FOXM1 activation induces the expression of genes linked to the hallmarks of cancer, cell proliferation, invasion, tumor growth, resistance mechanisms, immune escape, angiogenesis, and disease advancement." (PMID 39594778, 2024). "It is worth noting that the abnormal expression of FOXM1 in several malignant tumors is associated with poor prognosis, and targeting FOXM1 is considered as a potential therapeutic target for improving prognosis." (PMID 39711843, 2024). "FOXM1 is a TF critically associated with the cell cycle, considered a master regulator overexpressed in most human cancers." (PMID 38591003, 2024). "In several carcinomas, loss of FoxM1 leads to reduction of cancer invasion and migration by blockage of the EMT." (PMID 37968723, 2023). "FOXM1 activity has been implicated in various cancers, including breast, lung, and colorectal, and correlates with poor prognosis." (PMID 37835395, 2023). "The overexpression of FOXM1 in many human cancers is associated with advanced tumor stage, high proliferation rate, tumor aneuploidy, and poor prognosis." (PMID 37370117, 2023). "Increased expression of the cAMP-response element-binding protein (CBP)/β-catenin/FOXM1 transcriptional complex in TNBC cells in vivo was associated with a high proportion of cancer stem cells, high rates of drug resistance and poor survival outcome." (PMID 36424525, 2023). "Twelve tumors have a high likelihood to have FOXM1 as a risk factor, including three types of kidney malignancies, and a protective factor in one cancer (THYM)." (PMID 37401400, 2023). "Instead, their outcomes are associated with the upregulation of FOXM1 and increased genomic alterations in the cancers." (PMID 37452072, 2023). "FOXM1 gene amplification and activating mutations leading to its overexpression are reported in different cancers, contributing to almost all the hallmarks of cancer." (PMID 37025658, 2023). "The FOXM1 gene was the top gene most frequently associated with adverse risk in a pan-cancer analysis of 18,000 human tumors, and it outperformed MK167, which encodes the clinically used proliferation marker Ki-67." (PMID 37370117, 2023).